CTLA4 (cytotoxic T-lymphocyte associated protein 4)
Diseases named in the same sentence as CTLA4 in open-access papers (continued):
Sharing a sentence is not in itself a finding about the gene and the disease.
tumor (continued). "The advent of the so-called immunotherapy in oncology, in particular, antibodies against PD-1, PD-L1, and CTLA-4, have significantly modified the treatment, and consequently the history of many cancers, especially cancers with elevated tumor mutational burden, above all, neoplasms with MMRd/MSI." (PMID 36077639, 2022). "However, the anti-tumor response was significantly reduced when a mutation was induced in this full-sized antibody to generate a low-affinity construct for CTLA-4." (PMID 35326731, 2022). "They observed that anti-CTLA-4 mAbs with the same Fc variants employed in ipilimumab (IgG1) and tremelimumab (IgG2) both induced in vivo depletion of tumour infiltrating Treg cells in the context of human FcγRs, mainly in inflamed tumours with high FcγR-expressing innate effector cells." (PMID 35814459, 2022). "Thus, despite high expression of CTLA4, indicating late stage of antigen-experienced differentiation, a subset of tumor-associated expanded T cell clones remained capable of continued proliferation and expansion within the TME." (PMID 36185254, 2022). "Another approach used anti-CTLA-4 siRNA-loaded chitosan-lactate (CL) nanoparticles to facilitate priming anti- tumor T cells and the downregulation of CTLA-4 on tumor-infiltrating T cells were observed, which was associated with tumor regression and increased survival in a mouse tumor model." (PMID 36338731, 2022). "Furthermore, TCL6 is associated with tumor-infiltrating lymphocytes (TILs) and immunological checkpoint markers, including PD-1, PD-L1, PD-L2, and CTLA-4." (PMID 36207500, 2022). "Syngeneic tumor models have also been applied to the investigation of the anti-tumor activity of ICIs, including anti-programmed death (PD)-1/anti-PD-ligand 1 (L1) antibodies and anti-cytotoxic T lymphocyte-associated antigen 4 (CTLA-4)." (PMID 36012461, 2022). "Checkpoint inhibitors including nivolumab (anti-programmed cell death protein 1 (PD-1)), pembrolizumab (anti-PD-1), and ipilimumab (anti-cytotoxic T-lymphocyte-associated antigen-4 (CTLA-4)) are also tested in clinical trials for anti-tumor activity against CRPC." (PMID 35411277, 2022). "Normal CTLA-4 function may therefore cause inhibition of antitumor T-cells, and such a mechanism is hijacked by tumours allowing the evasion of anti-tumour immunity and thus facilitating tumour survival." (PMID 36498915, 2022). "However, recent clinical trials indicated that patients benefitting from anti-PD-1 antibody plus anti-CTLA-4 antibody were associated with a high tumour mutational burden." (PMID 35799269, 2022). "DCs also help to attract Tregs to the tumor and Tregs subsequently support this regulatory phenotype of DCs by expressing the inhibitory immunological checkpoint cytotoxic T-lymphocyte-associated protein 4 (CTLA-4) on a constant basis." (PMID 35392957, 2022). "For instance, it has been discussed that tumor regression caused by anti-CTLA-4 antibodies may rely on a selective reduction of Tregs." (PMID 36091050, 2022). "Immunosuppressive effects are maintained, aside from others, by the increased cell surface expression of immune checkpoint proteins (ICP) such as cytotoxic T-lymphocyte associated protein 4 (CTLA4) or programmed death ligand 1 (PD-L1) that counteract T-cell mediated tumor cell surveillance." (PMID 36077380, 2022). "At present, a series of important molecular determinants, including cytotoxic T lymphocyte antigen-4 (CTLA4), programmed death-ligand 1 (PD-L1), DNA mismatch-repair deficiency, and tumor-infiltrating lymphocytes (TILs), have been identified for this purpose in diverse types of cancer." (PMID 35883015, 2022). "Moreover, tumor immunotherapy is in the ascendant, encouraging us to start a new era of cancer treatment, mainly including programmed cell death 1 (PD-1) and cytotoxic T lymphocyte-associated antigen 4 (CTLA-4) checkpoint inhibitors." (PMID 36589233, 2022).
tumor (continued). "Understanding of host–tumor immune reaction led to the discovery of antibodies against immune checkpoint proteins, such as programmed death 1 (PD-1), its ligand PD-L1 and cytotoxic T-lymphocyte-associated protein 4 (CTLA-4)." (PMID 35326557, 2022). "While systemic anti-CTLA-4 therapy has the potential to disrupt tumor-associated immunosuppression through multiple pathways and at multiple sites, targeted delivery to TDLN has been shown in animal models to promote proportionally greater T-cell activation and systemic tumor control." (PMID 35621582, 2022). "T lymphocytes, like tumor cells, express immune inhibitory programmed cell death receptor-1 (PD-1), its ligand programmed death ligand-1 (PD-L1), and cytotoxic T-lymphocyte-associated protein 4 (CTLA-4), which is responsible for suppressing immune activity." (PMID 36060249, 2022). "Immune checkpoint blockers (ICBs), such as cytotoxic T lymphocyte-associated antigen 4 (CTLA-4) and programmed cell death 1 (PD-1) inhibitors, exert revolutionary effects on several tumors, while the efficacy seems to be closely related to the tumor immune microenvironment (TIME)." (PMID 35898512, 2022). "Studies showed that CTLA4 could regulate activation of T cells, and the high expression of this gene was notably associated with high levels of tumor-infiltrating lymphocytes." (PMID 39279987, 2022). "Interestingly, authors reported that, in mice, combination of telaglenastat with immune checkpoint inhibitors against PD-1 or CTLA-4 increased the number of tumor-infiltrating T cells and the expression of genes associated with IFN-γ signaling." (PMID 36713558, 2022). "GBM cells deliver immunosuppressive proteins such as CD73, CD39, programmed cell death ligand 1 (PD-L1), and cytotoxic T lymphocyte-associated protein 4 (CTLA-4) into the local microenvironment through extracellular vesicles, leading to immune cell function impairment and tumor progression." (PMID 36311702, 2022). "These hub genes showed remarkably associated with immune checkpoints (CD274, PDCD1 and CTLA4), which suggested that these hub genes may play an important role in tumor immune escape in HCC patients." (PMID 35637248, 2022). "Immunotherapy reverses the tumor-expressed extracellular ligands, which subdue intrinsic immune response, with cytotoxic T-lymphocyte-associated antigen 4 (CTLA-4, sometimes known as CD152) and programmed cell death protein-1 (PD-1 or CD279) as well as ligand PD-L1 being the classical examples." (PMID 35454923, 2022). "Effectively, MSI-H tumors express higher levels of tumor-infiltrating lymphocytes (TILs), cytotoxic T-lymphocyte-associated protein 4 (CTLA4), programmed cell death 1 (PD1)/PD-ligand 1 (PD-L1), indoleamine 2,3-dioxygenase (IDO), and lymphocyte-activation gene 3 (LAG-3)." (PMID 36294987, 2022). "Our results showed that the combination of oncolytic adenoviruses with anti-programmed cell death-ligand 1 (anti-PD-L1) and anti-cytotoxic T lymphocyte-associated antigen-4 (anti-CTLA-4) (aPC) can significantly inhibit tumour growth and prolong survival in a TNBC model." (PMID 34561555, 2022). "The ICOS pathway may have a more prominent role in anti-tumor activity than immunosuppression as ICOS/ICOSL-deficient mice show impaired anti-tumor activity in response to anti-CTLA-4." (PMID 35326731, 2022). "Several potential predictors of anti-PD-1 antibody response with favorable outcomes were investigated, such as CTLA4 promoter hypomethylation, PD-L1 expression, mismatch repair deficiency, tumor mutation burden, tumor-infiltrating immune cell features, and circulating immune cells." (PMID 36569825, 2022). "Meanwhile, anti-CTLA-4 therapy decreased the number of Tregs in tumor tissues, and it was significantly associated with favorable clinical events, implying that Tregs may mutually affect immune checkpoint molecules in immune regulation." (PMID 36119033, 2022).
tumor (continued). "Fractionated RT along with anti-CTLA4 produced abscopal effects caused in part by an increased number of Batf3 DCs, which were abolished in Batf3-/- mice, confirming the important role of Batf3 DCs in RT-induced anti-tumor immunity." (PMID 36532071, 2022). "Meanwhile, we found higher expression of PD‐1 and CTLA‐4 genes in high‐risk patients, suggesting that tumor immunogenicity may be stronger in the high‐risk group." (PMID 35373928, 2022). "Immunotherapies usually target the immune checkpoint blockade (ICB) through the use of monoclonal antibodies against inhibitory signaling molecules expressed on tumor and immune cells, such as programmed death-1 (PD-1), PD-1 ligand (PD-L1), and cytotoxic T-lymphocyte associated protein 4 (CTLA4)." (PMID 36359882, 2022). "In addition, by expanding the quantity, an antibody microarray confirmed that CTLA4 and Brevican remained significantly associated with tumor fibrosis." (PMID 35710350, 2022). "As loss of CTLA-4 may perturb immunosuppressive effects of Treg on tumor-infiltrating lymphocytes (TILs), it has been robustly proved that CTLA-4 blockade can support a paradigm shift in tumor therapy." (PMID 35392976, 2022). "Thus, the CSN5 inhibitor curcumin increases tumor cell susceptibility to CTLA4 therapy by lowering PD-L1 expression." (PMID 35907881, 2022). "Immune checkpoint inhibitors (ICIs) reduce immunosuppression in the tumor microenvironment and reactivate the anti-tumor function of T cells by inhibiting cytotoxic T lymphocyte-associated protein 4 and programmed cell death-1 pathway/programmed cell death receptor ligand-1 (PD-L1)." (PMID 36386191, 2022). "Tumor-infiltrating FoxP3+ Tregs play a direct role in promoting immune evasion by upregulating markers associated with activation and enhanced suppressive activity, including cytotoxic T-lymphocyte-associated protein 4 (CTLA-4), PD-1, and CD255,6." (PMID 35058524, 2022). "Moreover, double ICI combination, anti-cytotoxic T lymphocyte-associated antigen 4 (CTLA-4) agent, and anti-PD-1 agent combination therapy presented promising anti-tumor efficacy in MSI-H/dMMR mCRC." (PMID 36483562, 2022). "The relatively elevated levels of IPS-PD-11/CTLA4-blocker score in the high-risk patients indicated that individuals with high-risk scores might have higher tumor immunogenicity." (PMID 36189319, 2022). "In the current study, the motion pattern of tumor-associated immune cells was monitored as a functional response to PD-1 and CTLA-4 pathways to elucidate, at the cell-level temporal resolution, the kinetic constraints that potentially modulate the response to checkpoint blockade." (PMID 36428963, 2022). "In 2018, the Nobel prize for physiology or medicine was awarded to the Nobel Laureates who found two immune checkpoints: cytotoxic T-lymphocyte associated protein (CTLA-4) and programmed cell death protein 1 (PD-1) and its ligand (PD-L1) that are responsible for the tumor immune evasion." (PMID 34094974, 2021). "Recently, researchers have identified some important immune checkpoint components that promote the tumor cells to evade from the immune surveillance, such as cytotoxic T lymphocyte-associated protein 4 (CTLA-4) and programmed cell death protein 1 (PD-1)/programmed cells Death ligand 1 (PD-L1)." (PMID 34490269, 2021). "In some studies about certain solid tumors that lack IKZF1 expression, overexpression of Ikaros leads to increased immune recruitment infiltration and tumor sensitivity to cytotoxic T lymphocyte-associated antigen-4 (CTLA4) and programmed cell death protein 1 (PD1) inhibitors." (PMID 34950704, 2021). "Immune checkpoint inhibitors target immunosuppressive pathways such as programmed cell death protein 1 (PD-1) and cytotoxic T-lymphocyte-associated protein 4 (CTLA-4) that are upregulated in tumor-reactive T cells, thereby enhancing immune responses and endogenous anti-tumor activity." (PMID 33640005, 2021).
tumor (continued). "Upon binding to ligands CD80/CD86 expressed on APC and PD-L1 expressed on tumor cells, the immune checkpoint receptors, cytotoxic T-lymphocyte-associated protein 4 (CTLA-4) and PD-1, expressed on T cells induce inhibitory signals, leading to inactivation of T cells and immune evasion." (PMID 34359674, 2021). "The response to ICIs is influenced by several factors, which can be monitored using various biomarkers, including degree of CD8 + T cell infiltration, tumor mutation burden, mismatch repair, and the expression of critical immune checkpoints (PD-1, PD-L1, CTLA-4, LAG-3, TIM3, and TIGIT)." (PMID 34367952, 2021). "Antibodies that block immune regulatory checkpoints (programmed cell death 1, PD-1 and cytotoxic T-lymphocyte-associated antigen 4, CTLA-4) to mobilise immunity have shown unprecedented clinical efficacy against cancer, demonstrating the importance of antigen-specific tumour recognition." (PMID 33918976, 2021). "Targeting immune inhibitory molecules, including cytotoxic T-lymphocyte-associated protein 4 (CTLA-4), programmed death-1 (PD-1) and its ligand, PD-L1, aims to reinvigorate exhausted T cells, thus enabling improved tumor antigen recognition and cytotoxic activity." (PMID 34135901, 2021). "Recently, immune checkpoint inhibitors (ICIs) targeting programmed cell death protein (PD-1), programmed death-ligand (PD-L1), and T-lymphocyte-associated protein 4 (CTLA-4) have shown efficacies in restoring antitumor immunity in multiple tumor types with tolerable adverse-event profiles." (PMID 34692696, 2021). "Indeed, these modifications have been observed in various tumor tissues and have been associated with resistance to anti-PD-1/PD-L1 and anti-CTLA-4 immune checkpoint inhibitors." (PMID 34268109, 2021). "Anti-PD1 treatment seems to increase the risk for pneumonitis, hypothyroidism, myalgia and arthralgia, whereas for anti-CTLA-4 colitis and hypophysitis were more frequently described, and variations have been seen observed depending on the underlying tumor type." (PMID 34960142, 2021). "With the advent of immunotherapies, the tumor’s management has shifted from cytokine-based treatment to immune checkpoint inhibition, primarily of cytotoxic T-lymphocyte-associated antigen-4 (CTLA-4) and programmed cell-death protein 1 (PD-1) or its ligands (PD-L1 and PD-L2)." (PMID 33779796, 2021). "The best characterized inhibitory receptors on tumor-infiltrating lymphocytes (TILs) are programmed cell death protein 1 (PD-1), cytotoxic T lymphocyte associated-antigen 4 (CTLA-4), lymphocyte-activation gene 3 (LAG-3) and T cell immunoglobulin and mucin-domain containing 3 (TIM-3)." (PMID 34571883, 2021). "High CTLA-4+ TILs expression represents a mirror image to high density of stromal lymphocytes which help in tumour elimination; therefore, it is associated with pathological features of low tumour progression potential." (PMID 35047074, 2021). "In this case, decorating therapeutic EVs with antibodies specific for programmed death receptor-1 ligand (PD-L1) would direct them towards PD-L1-expressing tumor cells, while anti-cytotoxic T-lymphocyte-associated protein 4 (CTLA-4) antibodies would support regulatory T cell targeting." (PMID 34901032, 2021). "The most recent and reliable cancer therapies targeting CCIs are immune checkpoint inhibitors against cytotoxic T-lymphocyte-associated protein 4 (CTLA-4) and programmed cell death protein 1 (PD-1) or programmed cell death ligand 1 (PD-L1) by activating T cells to eliminate tumor cells." (PMID 34522794, 2021). "In addition, tumors appear to be more sensitive to anti-programmed death ligand 1 (PD-L1) and/or anti-cytotoxic T lymphocyte-associated protein 4 (CTLA-4) after inhibiting the RANK signaling pathway in tumor cells." (PMID 34831167, 2021).
tumor (continued). "In vivo experiments indicated that after treatment with FePt/BP-PEI-FA, combined with the anticytotoxic T lymphocyte-associated protein 4 (anti-CTLA4) checkpoint blockade, tumor immunity was greatly activated and led to complete inhibition of primary and metastatic tumors." (PMID 34656118, 2021). "On the other hand, multiple studies have indicated that high expression of PD-1/PD-L1 or CTLA-4 in the PDAC tumor microenvironment is associated with a worse outcome, suggesting that targeting CTLA-4 or the PD-1/PD-L1 interaction may yield therapeutic benefit." (PMID 33710604, 2021). "In the same vein, combination PD1 and CTLA4 therapy may be extended to other EBV-associated tumours that have significant populations of Treg and APCs expressing CTLA4." (PMID 34956172, 2021). "Moreover, blocking EZH2 expression by the pharmacological inhibitor CPI-1205 in MB49 tumor-bearing mice was associated with a better survival when combined with anti-CTLA-4." (PMID 34262562, 2021). "The cytotoxic function of tumor-infiltrating lymphocytes (TILs) is often impaired, for example by the activation of programmed cell death-1 (PD-1) and cytotoxic T-lymphocyte-associated protein-4 (CTLA4) receptors on T cells." (PMID 34073394, 2021). "Moreover, TMCs 4-8 were correlated with tumor mutation burden and expression of PD-1/PD-L1/CTLA4 in 33 cancers." (PMID 34899684, 2021). "They act by targeting immune checkpoints expressed by tumor infiltrating lymphocytes (TILs)—programmed-death 1 (PD-1) or cytotoxic T-lymphocyte-associated protein 4 (CTLA-4)—or expressed by cancer and tumor infiltrating immune cells—programmed-death ligand 1 (PD-L1)." (PMID 34205484, 2021). "Notably, combinational immunotherapy of anti-PD-1/anti-CTLA-4 treatment resulted in tumor regression, associated with the increased numbers of infiltrating lymphoid cells, robust T cell activation, and reduced hyperplasia in tumor-bearing lungs." (PMID 34277453, 2021). "However, we consider the blocking of anti-tumor activity is associated with cancer cell interaction with CTLA-4+ lymphocytes, thus, making the T cells of crucial importance, as far as MDA-MB-231 cells are considered." (PMID 34440813, 2021). "The therapeutic effect was more evident, with complete tumor regression, when the anti-CTLA-4 agent was associated with inhibitors of OX40 (TNF receptor mainly expressed on T lymphocytes), efficaciously reducing Tregs inside the tumor and increasing the activation and proliferation of CD8+ TILs." (PMID 34199722, 2021). "On the other hand there is significant association between high CTLA4 expression in tumor cells and poor prognostic parameters as advanced tumor stage (T4) and presence of vascular invasion (P= 0.01 and 0.05 respectively), also a trend of significance with advanced nodal stage (N2 and N3) (P= 0.07)." (PMID 33906311, 2021). "Acquired tumor immune suppression pathways through upregulation of the T cell checkpoint receptor PD-1 and cytotoxic T-lymphocyte-associated protein 4 (CTLA-4) in this Immunogenic subtype may offer therapeutic opportunities." (PMID 34805152, 2021). "Tumor mutational burden (TMB) is a key factor in determining the response of patients with cancer to immunotherapy with immune checkpoint inhibitors (anti-programmed cell death 1 [PD-1] or anti-cytotoxic T lymphocyte-associated antigen 4 [CTLA-4])." (PMID 34335558, 2021). "Ipilimumab and nivolumab are both antibodies that elicit an immune-mediated anti-tumour response upon binding to components of the immune system; specifically the cytotoxic T-lymphocyte-associated protein 4 (CTLA-4) and programmed cell death protein 1 (PD-1) receptor, respectively." (PMID 34900693, 2021). "Intriguingly, in the 4T1 spontaneous metastasis mouse model, some researchers found that receiving anti-CTLA-4 alone caused rapid motility of tumor infiltrating lymphocytes (TILs) in the tumor; local IR could also slightly enhance this motility." (PMID 32992835, 2020).